MIR4500HG (MIR4500 host gene)
Gene: Long non-coding RNA gene on chromosome 13 (87,427,183 to 87,674,235, reverse strand). Ensembl gene ENSG00000228824.
Diseases named in the same sentence as MIR4500HG in open-access papers:
MIR4500HG is named in the same sentence as 1 disease in open-access papers, as found by Europe PMC text mining. Sharing a sentence is not in itself a finding about the gene and the disease. The quoted sentences say what the papers report.
tumor (1 paper, 2021). "Each gene can predict tumor early recurrence from many patients, which confirmed the utility of SLFN13, RLTPR, HYDIN, MIR4500HG and TPRG1." (PMID 34395248, 2021). "Based on Lasso regression analysis, the expressions of five immune-related genes, RLTPR, SLFN13, MIR4500HG, HYDIN and TPRG1 were closely correlated with tumor early recurrence." (PMID 34395248, 2021). "Five immune-related genes, SLFN13, RLTPR, HYDIN, MIR4500HG and TPRG1, were identified to be closely correlated with tumor early recurrence." (PMID 34395248, 2021).